HIF1A (hypoxia inducible factor 1 subunit alpha)
Diseases named in the same sentence as HIF1A in open-access papers (continued):
Sharing a sentence is not in itself a finding about the gene and the disease.
cervical carcinoma (continued). "In summary, HIF-1α plays an important role in the growth, invasion, and metastasis of cervical cancer cells, and its mechanism may be involved in the occurrence and development of cervical cancer through its downstream tumor microenvironment-related proteins." (PMID 35664561, 2022). "In the third part, on the basis of the previous in vitro test, cervical cancer cells with knockdown and overexpression of HIF-1α gene were established by lentivirus transfection and injected into the subcutaneous (armpit) of nude mice to observe the effect on tumor formation in nude mice." (PMID 35664561, 2022). "YWHAG can interact with HIF-1α to affect the proliferation and invasion of cervical cancer cells." (PMID 35795276, 2022). "FDA approved topoisomerase inhibitor topotecan may affect HIF1A and is being used in the treatment of other forms of cancer such as lung, ovarian and cervical cancer and therefore may be suitable for repurposing for the treatment of bladder cancer." (PMID 35035776, 2022). "Furthermore, flavonoids have been shown to affect HIF-1 transcriptional activity by impairing the MAPK pathway, inhibiting nuclear accumulation and phosphorylation of HIF-1α in cervical cancer cells." (PMID 36077338, 2022). "In addition, the effect of YWHAG on cervical cancer cells is exerted through its interaction with HIF-1α, which then affects the PPP." (PMID 35795276, 2022). "To explore HIF-1α role in cell proliferation, invasion, and metastasis, we examined the changes of cell function in cervical cancer cells with HIF-1α overexpression and inhibition by MTT assay, wound healing assay, Transwell test, and other cell function tests." (PMID 35664561, 2022). "Therefore, we used lentivirus transfection technology to investigate the mechanism of HIF-1α in cervical cancer metastasis and the effect on Hippo pathway target and cervical cancer by cell functional level and molecular level." (PMID 35664561, 2022). "In sum, YWHAG interacted and was positively correlated with HIF-1α in cervical cancer cells." (PMID 35795276, 2022). "Hypoxia is a common feature in cervical cancer microenvironment, in which HIF-1α is accumulated." (PMID 35795276, 2022). "HIF-1α knockdown was found to enhance the radiosensitivity of Hela cervical cancer cells." (PMID 36313645, 2022). "Interestingly, HIF1α represents a key orchestrator of radioresistance and paclitaxel resistance of cervical cancer: even if these therapeutic approaches have various mechanisms of action, they all lead to an increase in ROS production." (PMID 33706793, 2021). "Similarly, in human cervical carcinoma cells (Hela), HIF-1α, IL-1β, IL-6, and IFN-β mRNAs were promoted by VSV infection, HSV-1 infection and poly(I: C) treatment and HIF-1α protein was induced by VSV infection, HSV-1 infection or poly(I: C) treatment." (PMID 34408131, 2021). "It was well know that hypoxia contributes to the Warburg effect through the regulation of expression of HIF-1α, whether OIP5-AS1 regulates the Warburg effect in cervical cancer cells through HIF-1α remains uncharacterized." (PMID 34513821, 2021). "Interestingly, only 50–60% of solid tumors exhibit hypoxic areas, and HIF-1α protein is instead decreased in severe hypoxic areas due to tumor necrosis in patients with cervical cancer and xenografted tumors." (PMID 32826949, 2020). "It is widely accepted that HIF-1α could turn on the switch of angiogenesis by cross talking with numerous growth factors, which is a crucial way to relive oxygen starvation of cervical cancer." (PMID 30915348, 2019). "In addition, a recent study demonstrated a promising effect of lapatinib (anti- EGFR and HER-2), in HER-expressing cervical cancer cells by reducing the number and size of blood vessels and preventing increased HIF-1α levels." (PMID 30760827, 2019). "Recent studies focused on the role of Hypoxia-Inducible Factor 1α (HIF-1α) in cervical cancer." (PMID 31350968, 2019).
cervical carcinoma (continued). "HOTAIR and HIF-1α expression in cervical cancer tissues and cells." (PMID 30355300, 2018). "To assess whether Met regulates the expression of HIF-1α-dependent proteins in cervical cancer cells we performed Western blot analysis." (PMID 29958416, 2018). "Radiation decreased the expression of HIF-1α in cervical tumor from mice and cervical cancer cells." (PMID 30355300, 2018). "In the present study, we further revealed that NF90 may be a regulator of VEGF-A expression through HIF-1α-dependent way under hypoxia in cervical cancer." (PMID 29449553, 2018). "Additionally, HIF1α inhibition leads to the downregulation of stem cell markers and a decrease in radioresistance of cervical cancer cells." (PMID 29688867, 2018). "Furthermore, miR-21 was shown to regulate the radiosensitivity of cervical cancer cells through the PTEN/AKT/HIF1α feedback loop and the AKT-mTOR signaling pathway." (PMID 29688867, 2018). "A. HOTAIR and HIF-1α expression was upregulated in cervical cancer tissues than normal tissues." (PMID 30355300, 2018). "In conclusion, the present study not only reveals that radiotherapy inhibits the cervical cancer cell growth through downregulating HOTAIR to inhibit the expression of HIF-1α, but also sheds new lights on the molecular mechanisms related to radioresistance of cervical cancer cell." (PMID 30355300, 2018). "However, the mechanism of how HOTAIR interacted with HIF-1α in cervical cancer cells exposed to radiotherapy needs to be further investigated." (PMID 30355300, 2018). "CSE also induced HIF-1α protein accumulation in the cervical carcinoma HeLa cell line." (PMID 27680676, 2016). "Based on a number of clinical studies, several investigators have promoted the view that the expression of HIF-1α and its target genes may be useful biomarkers of tumor hypoxia, aggressiveness, and radiation resistance in cervical carcinoma." (PMID 26502718, 2015). "Some clinical investigations have revealed that high expression of HIF-1α and/or CAIX may be associated with high incidence of lymph node metastases and poor metastasis-free survival rates in cervical cancer patients treated with radiation therapy." (PMID 26502718, 2015). "Lack of correlation between the extent of pimonidazole staining and the extent of HIF-1α or CAIX staining in cervical carcinoma may be a consequence of both tumor-specific conditions and tumor-independent mechanisms." (PMID 26502718, 2015). "However, another study showed that, despite the increased expression of HIF-1α, GLUT1 and CAIX in cervical cancer, only HIF-1α was associated with poor prognostic variables like lymph node metastasis and overall survival." (PMID 25296855, 2014). "In addition, HIF-1α is decreased by inhibiting ERK pathway in cervical carcinoma CaSki cells, but apoptosis is enhanced by HIF-1α knockdown in pancreatic cancerous BxPC-3 cells." (PMID 25491408, 2014). "Moreover, our previous studies have demonstrated that PI3K/Akt and ERK1/2 signaling pathways were involved in HPV-16 E6- and E7-induced HIF-1α protein accumulation in C-33A and HeLa cervical cancer cell lines." (PMID 25058399, 2014). "Although c-Met is well known to be regulated by HIF-1α in in vitro study, its association has not been confirmed with cervical cancer." (PMID 23927384, 2013). "HIF-1α expression was correlated with c-Met expression in cervical cancer (P < 0.001)." (PMID 23927384, 2013). "A correlation between HIF-1α expression and tumor oxygenation was found in cervical carcinomas." (PMID 22211243, 2012). "Similarly, upregulated circ-HIPK3 in cervical cancer cells sequesters miR-338-3p to increase the expression of HIF-1α, consequently enhancing the proliferation, colony formation, migration, and invasiveness of cervical cancer cells while suppressing their apoptosis." (PMID 40004471, 2025).
cervical carcinoma (continued). "Tandem mass tag proteomics and network pharmacology has shown that Hed may inhibit advanced cervical cancer cell mitochondrial autophagy by blocking the autophagy effector fraction through modulation of the target network, which is dominated by HIF-1α, Src, Akt, and Stat3." (PMID 38711526, 2024). "Thus, HIF-1α expression was promoted to increase the radioresistance of cervical cancer cells." (PMID 35692795, 2022). "Moreover, as a hypoxia-induced transcription factor, HIF-1α may also protect cervical cancer cells from radiation-induced apoptosis through various mechanisms." (PMID 35795276, 2022). "Cervical cancer data from TCGA were analyzed, and the correlation between YWHAG and HIF-1α in cervical cancer samples was measured using a microarray platform to investigate the proteins interacting with YWHAG that inhibit the proliferation of cervical cancer cells." (PMID 35795276, 2022). "Therefore, the current results suggest that OIP5-AS1 may be regulate Warburg effect through IDF2-mediated HIF-1α pathway by inhibiting miR-124-5p expression in cervical cancer." (PMID 34513821, 2021). "Radiotherapy might inhibit cervical cancer cell growth through HOTAIR/HIF-1α pathway." (PMID 30355300, 2018). "Interestingly, a recent study showed that E6 increases the protein stability of HIF1α through hindering the association of the von Hippel-Lindau tumor suppressor gene (VHL)-containing E3 ligase with its target HIF1α, resulting in induction of glycolysis in cervical cancer cells." (PMID 28881665, 2017). "Similarly, in cervical cancer low values for the DCE-MRI parameter ABrix were reported to be linked to a hypoxic tumor phenotype, demonstrated by upregulation of hypoxia response genes and increased HIF-1α protein expression." (PMID 27634881, 2016). "Importantly, HIF-1α was recently described as a predictor of poor prognosis in cervical cancer." (PMID 26525902, 2015). "Furthermore, our results confirmed the co-expression of HIF-1α and c-Met in cervical cancer." (PMID 23927384, 2013). "Although HIF-1α is known to influence deubiquitinases, its role in regulating ATXN3 in cervical cancer was previously unclear." (PMID 41507147, 2026). "FT has the capacity to hinder the growth of a tumor, reduce levels of HIF‐1α and VEGF mRNA, and protein expression in mouse cervical cancer." (PMID 40078339, 2025). "Another study was conducted to examine the impact and significance of FT on the level of hypoxia‐inducible factor‐1α (HIF‐1α) and vascular endothelial growth factor (VEGF) expression in cervical cancer tissue of mice." (PMID 40078339, 2025). "Protein expression and mRNA levels of HIF‐1α and VEGF showed remarkable inhibition in the mouse tissue cervical cancer FT and cisplatin groups compared to the positive control group." (PMID 40078339, 2025). "To assess the significance of HIF-1α expression in cervical cancer, we utilized the GEPIA2 database to visualize the mRNA expression levels of HIF-1α in cervical cancer." (PMID 38425341, 2024). "Circ-HIPK3 upregulates the expression of HIF-1α by adsorbing miR-338-3p, and HIF-1α mediates EMT to promote the growth and metastasis of cervical cancer cells." (PMID 37819576, 2023). "The expression of HIF-1α, VEGF-A and Ki67 proteins in tumor cells of cervical cancer pre- and post- chemotherapy." (PMID 37335690, 2023). "In the current study, we investigated the regulatory loop among HIFs (HIF-1α and HIF-3α) and miR-630 to identify their functions in cervical cancer progression." (PMID 36277475, 2022). "On the basis of our previous work, we used immunohistochemistry to detect the expression of HIF-1α and YAP/TAZ in normal cervical tissues, cervical intraepithelial neoplasia (CIN), and cervical cancer tissues." (PMID 35664561, 2022).
cervical carcinoma (continued). "This corresponds well to the HIF-1α-dependent, approximately 2- to 3-fold increase of FAM57A mRNA concentrations that we detected in our studies in hypoxic HeLa cervical cancer cells." (PMID 36291175, 2022). "The TCGA database of cervical cancer showed a positive correlation between YWHAG and hypoxia-inducible factor-1 subunit alpha (HIF-1α) expression." (PMID 35795276, 2022). "The experimental results in this part of the study are basically consistent with the relevant reports, indicating that HIF-1α and YAP/TAZ have certain value in the diagnosis of cervical cancer and the judgment of malignant degree and prognosis." (PMID 35664561, 2022). "At the same time, HIF-1α overexpression and HIF-1α inhibition cervical cancer cells were transplanted into nude mice, and tumors were isolated from the nude mice, and tumor volume and weight were observed." (PMID 35664561, 2022). "Increased expressions of HIF-1α, YAP, and TAZ in CSCC accelerate the development of cervical carcinoma." (PMID 35664561, 2022). "The results showed that after HIF-1α knockdown, the expression of YAP/TAZ decreased, and the invasion, migration, and proliferation of cervical cancer cells were weakened." (PMID 35664561, 2022). "The aim of this paper was to investigate the feasibility of PET imaging of hypoxia with 68Ga-Nitroimidazole in cervical cancer lesions and to correlate imaging findings to findings on 18F-FDG PET/CT as well as immunohistochemical staining for HIF-1α." (PMID 35207237, 2022). "The effect of HIF-1α on the expression of Hippo signaling pathway target gene YAP/TAZ and the function of cervical cancer cells during the occurrence and development of cervical cancer." (PMID 35664561, 2022). "Previous studies have shown that resveratrol can inhibit angiogenesis by targeting HIF-1α and VEGF in cervical cancers cells." (PMID 31143704, 2019). "In this study, we have demonstrated that, under normoxic conditions, the E6/E7 oncoproteins enhance expression of HIF-1α in HNSCC cells, as it was also reported for human cervical carcinoma cells." (PMID 30634708, 2019). "In cervical carcinoma HeLa cells, EGCG and green tea extract effectively inhibited the accumulation of hypoxia-induced HIF-1α protein through blocking PI3K/Akt and ERKs signal pathways, and promoted the degradation of HIF-1α protein via the proteasome system." (PMID 30213130, 2018). "Especially, increased expression of HIF-1α and its targets (e. g., vascular endothelial growth factor, hexokinases 2, and GLUT-1) have been reported to correlate with a worse prognosis in cervical cancer patients who received radiotherapy or chemoradiotherapy." (PMID 29109451, 2017). "In this study, we examined the correlation between mTOR, HIF-1α, c-Myc, and PKM2 expression and the response to cisplatin-based NACT in patients with stage IB2 or IIA2 cervical cancer." (PMID 27492148, 2016). "In this study, we demonstrated that mTOR, HIF-1α, c-Myc and PKM2 expression were significantly downregulated in post-chemotherapy cervical cancer tissues compared with matched pairs of pre-chemotherapy biopsies." (PMID 27492148, 2016). "To confirm these results, we further analyzed the tumor expression of mTOR, HIF-1α, c-Myc, and PKM2 in matched pairs of primary cervical cancer biopsies by western blotting analysis." (PMID 27492148, 2016). "In the present study, we first evaluated the effect of chemotherapy on the expression of mTOR, HIF-1α, c-Myc, and PKM2 in cervical cancer samples." (PMID 27492148, 2016). "Using paired tumor samples (pre- and post-chemotherapy) from 36 cervical cancer patients, we examined mTOR, HIF-1α, c-Myc, and PKM2 expression in cervical cancer samples and investigated the response to cisplatin-based NACT." (PMID 27492148, 2016).
cervical carcinoma (continued). "The current study also demonstrated that cisplatin decreased c-Myc and HIF-1α expression and strong c-Myc and HIF-1α expression was significantly correlated with a positive response to cisplatin-based NACT in patients with cervical cancer." (PMID 27492148, 2016). "In the present preclinical study, we challenged this view by searching for correlations between tumor hypoxia and the expression of HIF-1α and CAIX in CK-160 and TS-415 cervical carcinoma xenografts." (PMID 26502718, 2015). "Especially, our previous study has demonstrated that HPV-16 E6 and E7 induced HIF-1α protein accumulation and VEGF expression via PI3K/Akt signaling pathway in human cervical cancer cells." (PMID 25058399, 2014). "HIF-1α, c-Met, CA9 and GLUT1 expression were higher in cervical cancer than in CIN and normal cervix (all P < 0.001)." (PMID 23927384, 2013). "In the current study, the expression of HIF-1α and functionally related proteins, including c-Met, CA9 and GLUT1, were analyzed in cervical cancer patients by combined IHC and automated digital image analysis." (PMID 23927384, 2013). "In previous studies performed on patients with cervical cancer, prognostic significance of HIF-1α was inconsistent, even though the HIF-1α is involved in tumor cell metabolism, invasion and metastasis." (PMID 23927384, 2013). "Of 179 cervical cancer specimens, 148 (82.6%) was available to confirm co-expression between HIF-1α and c-Met, 131 (73.1%) was available between HIF-1α and CA9, and 137 (76.5%) was available between HIF-1α and GLUT1." (PMID 23927384, 2013). "After establishing HOTAIR’s role in modulating key signaling pathways in cervical cancer (CC), we conducted a meta-analysis that revealed elevated levels of PI3K, AKT, HIF1α, and β-catenin proteins in CC tumor samples compared to healthy controls, alongside reduced levels of GSK3β." (PMID 39273054, 2024). "However, a recent study reported that PX-478, an inhibitor of HIF-1α, significantly degrades the cytotoxic activity of mesothelin-CAR-T-cells (meso-CAR-T-cells) targeting cervical cancer cells and induces T-cell exhaustion." (PMID 39421736, 2024). "Furthermore, research has demonstrated that LQ can downregulate the expression of HIF-1a and VEGF in human cervical cancer cells through the VEGF signaling pathway, thereby exerting an anti-angiogenic effec." (PMID 38751791, 2024). "As we only assessed a subset of responses using an isolated cell system, our results should not be interpreted as evidence for negative impacts of HIF-1α inhibitors in cervical cancer more broadly." (PMID 38425341, 2024). "Moreover, HIF1A and S100A2 are upregulated and can possibly account for miR-21 overexpression to explain in part the aggressive cervical cancer phenotype progression." (PMID 38612895, 2024). "Additionally, Sindilizumab inhibited the expression of tissue-type fibrinogen activator K and HIF1α through the PD-1/IRE1α/SHP2 signaling pathway, which inhibited the migration and neovascularization of cervical cancer cells." (PMID 39207449, 2024). "What’s more, in the response group, HIF-1α, VEGF-A, and Ki67 expression were significantly decreased after chemotherapy in the post-chemotherapy cervical cancer tissues compared with the pre-chemotherapy cervical cancer tissues (all P < .05)." (PMID 37335690, 2023). "Hypoxia is a component of the tumor microenvironment in solid tumors and cervical cancer is no exception, and the presence of HIF-1α indirectly upregulates CAF’s and their pro-angiogenic functions in hypoxic states." (PMID 37568769, 2023). "Moreover, circCCDC134 showed a dual tumor-promoting mechanism in cervical cancer by either recruiting p65 in nucleus or serving as a miR-503-5p sponge to regulate the expression of MYB in cytoplasm, ultimately enhancing HIF1A transcription." (PMID 37495592, 2023).